BMI1 (BMI1 proto-oncogene, polycomb ring finger)
Diseases named in the same sentence as BMI1 in open-access papers (continued):
Sharing a sentence is not in itself a finding about the gene and the disease.
bladder cancer (continued). "Further biological analyses of The Cancer Genome Atlas (TCGA) database revealed BMI1 was increased in bladder cancer patients resistant to chemotherapy, which confers tumor relapse and progression." (PMID 34270461, 2021). "A genomics approach revealed an 11-gene signature (including BMI1) that consistently displayed a stem-cell-resembling expression profile in distant metastatic lesions of different cancers, including bladder cancers." (PMID 30072631, 2018). "Overexpression of the oncogene BMI1 in bladder cancer, and CSCs, as well as in various other human cancers has been associated with aggressive tumor behavior and poor outcome." (PMID 29220397, 2017). "MiR-200c was shown to inhibit invasion, migration, and proliferation of bladder cancer cells through down-regulation of BMI-1 and E2F3." (PMID 28978061, 2017). "It was demonstrated that miR-200c was significantly diminished in bladder cancer tissues and appeared to control the EMT process of bladder cancer cells via regulation of BMI-1 and E2F3." (PMID 28947999, 2017). "DEA also inhibits the expression of B-cell-specific Moloney murine leukemia virus integration site 1 (BMI1) and reduces colony formation of T24 bladder carcinoma cells, indicating its possible inhibitory effect on metastatic potential." (PMID 29220397, 2017). "And up-regulation of miR-200c decreased the BMI-1 gene expression, which inhibited the process of bladder cancer." (PMID 25367080, 2014). "The current study has indicated that miR-200c is a tumor-suppressive miRNA in bladder cancer, and that oncogene and transcription promoters, namely, BMI-1 and E2F3, are functional targets of miR-200c." (PMID 25367080, 2014). "BMI-1, as a molecule of accelerating tumor progress, will promote proliferation of bladder cancer cells." (PMID 25367080, 2014). "Here, our results indicated that BMI1 expression displayed correlation with the clinic-pathological features of the bladder cancers, and BMI1 expression in invasive bladder cancer was significantly higher than that in superficial bladder cancer." (PMID 23820733, 2013). "We have demonstrated here, that by using siRNA to silence BMI1 expression, the p16 and p14 expression are increased, which in turn inhibited cell growth in bladder cancer." (PMID 23820733, 2013). "In conclusion, our results have demonstrated that BMI1 promoted proliferation, migration, invasion, and progression in bladder cancer." (PMID 23820733, 2013). "A prior study found that BMI1 was highly expressed in bladder cancer, and served as a prognostic marker in bladder cancer, supporting our results on BMI1 expression in bladder cancer." (PMID 23820733, 2013). "We demonstrated here that BMI1 promoted bladder cancer cell proliferation, migration, and progression by inhibition p16 and p14 expression." (PMID 23820733, 2013). "To determine the role of BMI1 in cancer cells, we transduced BMI1 siRNA into bladder cancer T24 cells." (PMID 23820733, 2013). "So, the precise molecular mechanism of BMI1 in the tumorigenesis and proliferation of bladder cancer needs to be further explored." (PMID 23820733, 2013). "Our results revealed that BMI1 promoted proliferation, migration, invasion, and progression in bladder cancer." (PMID 23820733, 2013). "In this study, we investigated the effects of BMI1 knockdown on the proliferation, apoptosis, and invasive in bladder cancer T24 cells." (PMID 23820733, 2013). "In this study, we found that BMI1 was highly expressed in bladder cancer and its expression was correlated with clinic-pathological features." (PMID 23820733, 2013). "IHC staining showed that 53.5 % (38/71) of bladder cancer tissues were moderately or strongly positive for BMI1 staining, which was expressed in the neoplastic epithelial cell nuclei." (PMID 23820733, 2013). "To address this question, we examined the expression of BMI1 in bladder cancer tissues and used siRNA to knockdown BMI1 expression in bladder cancer T24 cells." (PMID 23820733, 2013).
bladder cancer (continued). "Expression of Bmi-1 mRNA and protein was higher in bladder cancers than in the adjacent normal tissues in 14 paired samples (P < 0.01)." (PMID 19228380, 2009). "The expression of Bmi-1 protein in 137 specimens of bladder cancer and 30 specimens of adjacent normal bladder tissue was determined by immunohistochemistry." (PMID 19228380, 2009). "Expression and subcellular localization of Bmi-1 protein were determined by immunohistochemistry in 137 paraffin-embedded bladder cancer tissues, and 30 specimens of adjacent normal bladder tissues." (PMID 19228380, 2009). "In our study, we found that in addition to T classification and TNM stage, Bmi-1 expression is an independent prognostic factor for bladder cancers." (PMID 19228380, 2009). "The relative level of Bmi-1 expression was compared in bladder cancers and the adjacent normal tissue." (PMID 19228380, 2009). "In this study we aimed to explore the expression of Bmi-1 protein and its clinical significance in human bladder cancers." (PMID 19228380, 2009). "By immunohistochemical examination, five of 30 adjacent normal bladder specimens (16.7%) versus 75 of 137 bladder cancers (54.3%) showed Bmi-1 protein expression (P < 0.05)." (PMID 19228380, 2009). "To ensure the reliability of this study, we first examined the expression of Bmi-1 mRNA and Bmi-1 protein by RT-PCR and Western blot, respectively in 14 bladder cancers." (PMID 19228380, 2009). "The examination of Bmi-1 protein expression is potentially valuable in prognostic evaluation of bladder cancer." (PMID 19228380, 2009). "The expression level of Bmi-1 protein in bladder cancer was significantly correlated with patient survival (P < 0.001), and the correlation coefficient was -0.27, indicating that a higher level of Bmi-1 expression was correlated with shorter survival time." (PMID 19228380, 2009). "We examined the expression of Bmi-1 mRNA and Bmi-1 protein by RT-PCR and Western blot, respectively in 14 paired bladder cancers and the adjacent normal tissues." (PMID 19228380, 2009). "Consistent with previous reports of other cancers, over-expression of Bmi-1 protein indicated poor prognosis for patients with bladder cancer." (PMID 19228380, 2009). "Intense expression of Bmi-1 in bladder cancer was positively correlated with the histopathological classification, clinical stage, and recurrence (P < 0.05); but was not correlated with gender, age, or tumor number (P > 0.05)." (PMID 19228380, 2009). "The objective of this study was to analyze the expression of Bmi-1 protein and its clinical significance in human bladder cancer." (PMID 19228380, 2009). "Bmi-1 protein expression was high in 54.3% of bladder cancers, while Bmi-1 expression was observed in only 16.7% of adjacent normal tissues (P < 0.05)." (PMID 19228380, 2009). "This study demonstrated that there was a significant difference in Bmi-1 expression at both protein and mRNA levels between bladder cancer cells and the adjacent normal bladder tissue." (PMID 19228380, 2009). "Prospective studies, additional cases, and different antibodies would be required to test the relationship between Bmi-1 expression and the clinical biological behavior of bladder cancer." (PMID 19228380, 2009). "Additionally, betulinic acid induced autophagy and apoptosis in bladder cancer cells through the Bmi-1/ROS/AMPK/mTOR/ULK1 axis." (PMID 35897796, 2022). "Moreover, miR-200c regulated EZH2 through BMI-1 and E2F in breast, lung, prostate, bladder cancers and hepatocarcinoma." (PMID 36316365, 2022). "Polycomb complex protein Bmi-1 was demonstrated to be a prognostic marker in bladder cancer." (PMID 34510030, 2021). "To assess whether Bmi-1 expression counteracts BA-induced ROS production, migration inhibition, and autophagy induction in bladder cancer cells, we overexpressed Bmi-1 via lentiviral transfection." (PMID 34510030, 2021).
bladder cancer (continued). "BMI1 up-regulation, which could be attributed to the amplification of gene loci on the 10p12.2 chromosome, was related to the relapse and progression of bladder cancer." (PMID 34270461, 2021). "This study demonstrated that the elevated BMI1 expression observed in GC-resistant patients with bladder cancer could be due to genomic amplification of 10p12.2, which conferred poor prognosis." (PMID 34270461, 2021). "Furthermore, the expression level of BMI1 was an independent prognosis factor for bladder cancer (P < 0.05) similar to clinical grade, stage, multiplicity and LN metastasis." (PMID 34270461, 2021). "These experiments showed that miR-3682-3p could directly inhibit ABCB1 gene through targeting its 3'-UTR, contributing to BMI1-mediated chemoresistance of bladder cancer cells." (PMID 34270461, 2021). "Furthermore, a study in bladder cancer reported that miR-218 not only suppresses BMI-1, but also upregulates PTEN, thereby reducing the levels of phosphorylated AKT." (PMID 33120864, 2020). "Several other studies revealed the potential roles of miR-200c in bladder cancer metastasis, and overexpression of miR-200c significantly inhibited invasion and migration of bladder cancer cells and led to conspicuous reduction of BMI-1 and E2F3." (PMID 28947999, 2017). "To this, we transiently overexpressed human BMI1 protein in RT112 bladder cancer cells." (PMID 26517683, 2015). "Together, these results demonstrate a progressive diminution of miR-200c expression in bladder cancer compared with coordinated normal bladder tissues and suggest a further reduction in expression during bladder cancer progression, and BMI-1 expression correlates inversely with miR-200c expression." (PMID 25367080, 2014). "We asked whether enforced expression of miR-200c would also affect BMI-1 expression in bladder cancer cells." (PMID 25367080, 2014). "Our results revealed a close, direct association between expression of miR-200c, BMI-1, E-cadherin, N-cadherin, P14, P16 and E2F3 expression, representing a pivotal cellular axis impacting not only the capacity of bladder cancer cells to metastasize but also the ability of proliferation." (PMID 25367080, 2014). "BMI1 siRNA effectively inhibited bladder cancer cell proliferation and migration in vitro, and it promoted bladder cancer invasion, maybe by causing EMT." (PMID 23820733, 2013). "Furthermore, BMI1 siRNA in bladder cancer T24 cells reduced the migration of bladder cancer in vitro." (PMID 23820733, 2013). "Combined with our study, all these supported the idea that BMI1 promoted the invasion and migration of bladder cancer maybe through acquiring EMT characteristics." (PMID 23820733, 2013). "Knockdown of endogenous BMI1 expression reduced bladder cancer proliferation and invasiveness." (PMID 23820733, 2013). "Because of the significance of BMI1 in cancers tumorigenesis, we hypothesis it may play an important role in bladder cancer tumorigenesis and metastasis." (PMID 23820733, 2013). "BMI1 siRNA effectively inhibited bladder cancer cell proliferation and migration in vitro, and it promoted bladder cancer invasion, maybe by causing epithelial-to-mesenchymal transition." (PMID 23820733, 2013). "However, they are unclear as to the molecular mechanism of how BMI1 influences bladder cancer development, how BMI1 promotes bladder cancer proliferation and migration." (PMID 23820733, 2013). "To determine whether BMI1 suppresses the expression of p16 and p14 in bladder cancer, we used siRNA to silence BMI1 expression, and then detected the expression of p16 and p14." (PMID 23820733, 2013). "Expression of Bmi-1 was greater in bladder cancers than in the adjacent normal tissues." (PMID 19228380, 2009).
bladder cancer (continued). "Furthermore, intense expression of Bmi-1 in bladder cancer correlated with its clinicopathologic features including tumor classification, recurrence, and TNM stage." (PMID 19228380, 2009). "In this study, we report that Bmi-1 is overexpressed in human bladder cancers." (PMID 19228380, 2009). "Thus, our findings indicate that the Bmi-1 protein expression level has a significant correlation with clinicopathological features, and is a potential prognostic marker for bladder cancer." (PMID 19228380, 2009). "In addition, we can say only that Bmi-1 expression is an independent prognostic marker for bladder cancer." (PMID 19228380, 2009). "This study demonstrated overexpression of Bmi-1 in bladder cancers." (PMID 19228380, 2009). "Thus, we believe that the BMI1 gene probably plays an important role in cell proliferation and tumor progression in bladder cancers." (PMID 19228380, 2009). "Moreover, suppression of P-GP by miR-3682-3p mimics or XR-9576 could significantly reverse BMI1-mediated chemoresistance of bladder cancer cells." (PMID 34270461, 2021). "Suppression of P-GP by miR-3682-3p mimics or XR-9576 could significantly reverse BMI1-mediated chemoresistance of bladder cancer cells, presenting miR-3682-3p or XR-9576 as a potential adjuvant agent in GC-chemoresistant bladder cancer with ectopic BMI1 expression." (PMID 34270461, 2021). "However, the mechanisms of how BMI1 functions to promote bladder cancer progress remain elusive." (PMID 23820733, 2013). "In bladder cancer, SNHG3 regulates c-MYC to stabilize BMI1 mRNA, highlighting its role in tumorigenesis and proposing the SNHG3/c-MYC/BMI1 axis as a novel therapeutic target." (PMID 39349640, 2024). "Research showed that NaB inhibited bladder cancer cell migration and induced AMPK/mTOR pathway-activated mitophagy and ROS overproduction through the miR-139-5p/Bmi-1 axis, while ROS overproduction contributed to NaB-induced cysteine-dependent apoptosis." (PMID 37686278, 2023). "In this study, we established T24/DDP&GEM cells resistant to cisplatin and gemcitabine, and investigated the regulation role of BMI1/miR-3682-3p/P-GP axis in T24/DDP&GEM cells and in bladder cancer tissues of patients resistant to GC chemotherapy." (PMID 34270461, 2021). "In contrast, depletion of ARRB1 in bladder cancer cells abrogated expression of CD44 and resulted in significantly reduced protein levels of Bmi1." (PMID 33297302, 2020). "Moreover, in bladder cancer, it has been reported that miR-200c is downregulated in cancer specimens compared with adjacent tissues in the same patients, and miR-200c could inhibit bladder cancer cell invasion through direct targeting of BMI-1 and E2F3." (PMID 31240993, 2019). "Then, the expression of previously identified bladder cancer stem cell markers (POU5F1, BMI1, NANOG, SOX2,) was determined by real- time qPCR in the established control NT and αv kd cell lines as well as in GLPG0187 treated cells." (PMID 25247809, 2014). "In this study, we found that down-regulated expression of miR-200c and up-regulation of its direct target BMI-1 and E2F3 in bladder cancer tissue and cell lines." (PMID 25367080, 2014). "Consistently, in another two bladder cancer cells, T24 and BIU-87, miR-3682-3p was detected by q-RT-PCR to be highly expressed upon BMI1 knockdown, whereas miR-3682-3p was down-regulated after overexpressing BMI1." (PMID 34270461, 2021). "Using in vitro and in vivo approaches, in this study we evaluated the effects of BA on human bladder cancer cell proliferation and migration and examined the role of ROS, the AMPK-mTOR-ULK1 cascade, and Bmi-1 in autophagy-dependent apoptosis triggered by BA exposure." (PMID 34510030, 2021).
bladder cancer (continued). "In agreement, knockdown of EZH2 in RT112 bladder cancer cells produced the overall upregulation of all miR-200 members without significant changes in BMI1 protein." (PMID 26517683, 2015). "Over-expression of BMI1 or deletions of p16 and p14 are frequently discovered in many cancers, but their roles in bladder cancer have not been previously recognized." (PMID 23820733, 2013). "Immunohistochemistry demonstrated that bladder cancers showed moderate to strong nuclear staining, while adjacent normal tissues showed only weak Bmi-1 expression, or no Bmi-1 expression at all." (PMID 19228380, 2009). "Importantly, bladder cancer with BMI1 amplification predicted a worse survival than those without BMI1 amplification (P = 0.0383)." (PMID 34270461, 2021). "Besides, previous studies found that the down-regulation of miR-200c and miR-141 is associated with elevated ZEB1, and the down-regulation of miR-200c is also coupled with the down-regulation of BMI-1 and E2F3, which play an important role in the invasion, migration, and EMT of bladder cancer." (PMID 30323832, 2018). "However, there is no study about the issue on the role of BMI1 in the proliferation, apoptosis, and migration of bladder cancer." (PMID 23820733, 2013). "Because BMI1 was higher expression in invasive bladder cancer than in non-invasive bladder cancer, we hypothesized that BMI1 regulated the invasive and migration abilities of bladder cancer." (PMID 23820733, 2013). "However, there is no published report on the expression of Bmi-1 in bladder cancer." (PMID 19228380, 2009).